FCN3 (ficolin 3)
Description:
Calcium-dependent lectin, which acts as a pattern recognition receptor that initiates the lectin pathway of the complement system, a cascade of proteins that leads to phagocytosis and breakdown of pathogens and signaling that strengthens the adaptive immune system. Specifically recognizes and binds carbohydrates on the pathogen surface, activating the MASP1 serine protease and initiating the proteolytic cascade of the lectin complement pathway. Specifically binds N-Acetylglucosamine (GlcNAc,) GalNAc (N-acetylgalactosamine) and D-fucose on the surface of pathogens, as well as mono/oligosaccharide and lipopolysaccharides from S.typhimurium and S.minnesota.
Synonyms: FCNH; HAKA1
Tractability: Small molecule: a structure with a bound ligand is known; it has a high-quality binding pocket. Antibody: its Gene Ontology location is reachable by antibodies, with high confidence; UniProt places it where antibodies can reach, with medium confidence; UniProt predicts a signal peptide or a membrane-spanning region.
Gene: Protein-coding gene on chromosome 1 (27,369,108 to 27,374,854, reverse strand). Ensembl gene ENSG00000142748.
Subcellular location: Secreted; Cell surface
Pathways (Reactome):
Immune System: Ficolins bind to repetitive carbohydrate structures on the target cell surface; Initial triggering of complement; Lectin pathway of complement activation
Gene Ontology:
Molecular function: antigen binding; carbohydrate derivative binding; pattern recognition receptor activity; protein binding; carbohydrate binding; signaling receptor binding
Biological process: complement activation; complement activation, lectin pathway; defense response to virus; host-mediated suppression of symbiont invasion; negative regulation of RNA biosynthetic process; positive regulation of opsonization; proteolysis; recognition of apoptotic cell; cell surface pattern recognition receptor signaling pathway
Cellular component: blood microparticle; cell surface; extracellular region; serine-type endopeptidase complex; symbiont cell surface; external side of plasma membrane; extracellular matrix
Genetic constraint (gnomAD): Loss-of-function variants: 29 observed, 32.51 expected, observed/expected ratio (o/e) 0.89, 90% interval 0.66 to 1.22. The upper end of that interval is the gene's LOEUF score, 1.22, which puts it in group 5 of 6, group 1 being the genes least tolerant of losing a copy. Missense variants: 351 observed, 386.1 expected, observed/expected ratio (o/e) 0.91, 90% interval 0.83 to 0.99. Synonymous variants: 124 observed, 146.99 expected, observed/expected ratio (o/e) 0.84, 90% interval 0.73 to 0.98.
Homologues: Orthologues: macaque FCN3 (96% identical), chimpanzee FCN3 (70% identical). Paralogues in human: FCN1 (48% identical), FCN2 (48% identical), TNR (42% identical), TNXB (41% identical), TNC (40% identical), TNN (38% identical), FGL2 (34% identical), ANGPTL2 (33% identical), FIBCD1 (33% identical), ANGPTL6 (33% identical), FGB (32% identical), MFAP4 (31% identical), and 13 more.
Diseases named in the same sentence as FCN3 in open-access papers:
FCN3 is named in the same sentence as 104 diseases in open-access papers, as found by Europe PMC text mining. Sharing a sentence is not in itself a finding about the gene and the disease. The quoted sentences say what the papers report.
hepatocellular carcinoma (10 papers, 2020 to 2026). A malignant tumor that arises from hepatocytes. "Research conducted previously indicates that the levels of FCN3 expression were notably reduced in various cancerous tissues, including squamous cell lung carcinoma, hepatocellular carcinomas, and ovarian cancer." (PMID 40297163, 2025). "It has been shown that the expression of the FCN3 gene is lower in the case of different cancers, and a recent study demonstrated that hepatocellular carcinoma patients with a high FCN3 expression had a significantly better overall survival." (PMID 38338844, 2024). "Here, we found that FCN3 expression was significantly downregulated in hepatoma cells and HCC tissues on both mRNA and protein level and that FCN3 function as a tumor suppressor." (PMID 36632465, 2023). "Nevertheless, the clinical significance of FCN3 in patients with hepatocellular carcinoma (HCC) is unclear." (PMID 37484802, 2023). "Notably, the liver-specific overexpression of FCN3 reduced the incidence of hepatocellular carcinoma." (PMID 38698462, 2024). "FCN3 suppresses the progression in lung and liver carcinoma by inhibiting apoptosis." (PMID 38698462, 2024). "In summary, this study clarified the biological function of FCN3 in hepatoma cells." (PMID 36632465, 2023). "We demonstrate that FCN3 overexpression efficiently sensitizes HCC cells to ferroptosis by downregulating MUFA levels, leading to the inhibition of the oncogenesis and progression of both primary hepatocellular carcinoma and subcutaneous HCC xenograft." (PMID 38698462, 2024). "Next, we aim to investigate the in vivo anticancer effects of FCN3 using mouse models with primary hepatocellular carcinoma or subcutaneous HCC xenografts." (PMID 38698462, 2024). "In liver hepatocellular carcinoma (LIHC) cohort, the expression of FCN3 was significantly downregulated in HCC tissues compared to unpaired or paired liver tissues." (PMID 36632465, 2023). "Primary hepatocellular carcinoma (HCC) and xenograft models were utilized to investigate the effect of FCN3 on the development of HCC in vivo." (PMID 38698462, 2024).
COVID-19 (9 papers, 2021 to 2025). A disease caused by infection with severe acute respiratory syndrome coronavirus 2. "In particular, mutations in TNFRSF13B, UBA1, IRF2BP2, and FCN3 were already reported to be associated with severe COVID-19." (PMID 36552859, 2022). "Increased MBL and ficolin expression (e.g., FCN-3) in COVID-19 further support lectin pathway activation." (PMID 40508203, 2025). "In a small study, increased FCN3 concentrations were observed in severe COVID-19 in Asian patients with significant renal disease." (PMID 34777382, 2021). "The comparison of postmortem lungbiopsies of COVID-19 and H1N1 patients and control patients who died of causesnot involving lung lesions showed higher expression of FCN3 (ficolin 3) in bothdiseases compared to the control group." (PMID 34436508, 2021). "Notably, nine patients harbored the same FCN3 variant identified in three of our patients (rs532781899), four in the non-admitted COVID-19 group and 5 in the admitted group, but none in the MIS-C group." (PMID 37588055, 2023). "The present study is the largest study to assess serum MBL, ficolin-3 and C1INH concentrations as well as CP, AP and LP activity in a well-characterized cohort of COVID-19 patients." (PMID 34777382, 2021).
diabetes (9 papers, 2008 to 2025). "A recent study indicated that elevated FCN3 levels were linked to an increased risk of diabetes-related mortality." (PMID 38375199, 2024). "Our research identified a significant decrease in FCN3 levels, which may have a beneficial impact on reducing long-term complications associated with diabetes." (PMID 38375199, 2024). "Additionally, in patients with pre-diabetes and type 2 diabetes, HIIT was found to be a more time-efficient strategy than MICT as serum ficolin-3 levels (associated with diabetes) decreased after 3 weeks of HIIT training." (PMID 36837817, 2023). "Accordingly, the objective of our study was to provide complex observational data on the lectin pathway focusing on the ficolin-3-mediated pathway in diabetes mellitus in the context of community acquired bacterial infections." (PMID 30949171, 2019). "In order to evaluate the correlation of ficolin-3 with diabetes, the protein-abundance of ficolin-3 was validated by Western blotting in additional clinical sera from 24 non-diabetic subjects and 24 diabetic patients." (PMID 18795103, 2008). "It has been found that FCN3 is related to insulin resistance and diabetes." (PMID 34366831, 2021). "Another member of the ficolin family; ficolin-3 (FCN3), which shares approximately 50% amino acid sequence homology with FCN2, is also associated with insulin resistance and diabetes." (PMID 30618716, 2018).
ovarian carcinoma (8 papers, 2013 to 2025). A malignant neoplasm originating from the surface ovarian epithelium. "Michalskia studies suggest that FCN3 may be involved in the immune response to ovarian cancer and that its expression is associated with the development of ovarian cancer." (PMID 35928441, 2022). "We later found elevated serum Ficolin-2 (L-ficolin) and Ficolin-3 (H-ficolin) in ovarian cancer patients, while the local expression of the corresponding genes was decreased." (PMID 25038892, 2014). "Studies have shown that the abnormal expression of FCN3 in esophageal cancer, ovarian cancer and other tumors may participate in the host cancer immune response process." (PMID 34277395, 2021).
Stroke (8 papers, 2011 to 2021). Sudden impairment of blood flow to a part of the brain due to occlusion or rupture of an artery to the brain. "Nevertheless, taken together, these data implicate a role for ficolin-3 in stroke although its specific prognostic value still needs to be clarified." (PMID 26792363, 2016). "In ischemic stroke, serum ficolin-3 levels are inversely correlated with the severity of stroke indicated by the National Institute of Health stroke scale on admission and the concentrations of S100b, an indicator of the size of cerebral infarct." (PMID 26627059, 2015). "Concentrations of ficolin-2 and ficolin-3 were even higher in patient controls than in healthy subjects, indicating that the decreased levels in sera during the acute phase of stroke are related to the acute ischemic event." (PMID 22206485, 2011). "Compared to both healthy controls and patient controls, both ficolin-2 ficolin-3 levels were significantly lower both in the admission and follow-up sera of stroke patients." (PMID 22206485, 2011). "The differences observed between stroke patients and healthy individuals seem to be valid, since the ficolin-2 and ficolin-3 concentrations measured in the sera of healthy subjects are similar to previously reported data." (PMID 22206485, 2011). "In addition, ficolin-2 and ficolin-3 levels were significantly lower in sera of patients with definite stroke compared to patients with severe carotid atherosclerosis without clinical event as well." (PMID 22206485, 2011). "Some of the stroke subtype-specific proteins (FBLN1, F2, SERPINF2, CBP2, FCN3, GPX3, IKG, and GSN) were also affected by the CBS deficiency." (PMID 31242583, 2019). "In stroke patients, the LP was shown to be the relevant pathway in the progression of ischemic brain damage with studies highlighting MBL and ficolin-3, two different LP recognition molecules, as independent predictors of ischemic stroke outcome." (PMID 27577570, 2016).
leprosy (7 papers, 2017 to 2025). Leprosy is a chronic infectious disease affecting primarily the skin and peripheral nervous system. "It was evidenced that higher FCN3 serum levels were associated with early and transient clinical forms and lower expression in severe forms of leprosy." (PMID 35622698, 2022). "Higher serum FCN3 levels were associated with the early and transient clinical forms of leprosy and lower expression in severe forms of the disease." (PMID 35622698, 2022). "In comparison, another study did not observe an association between the polymorphism of the FCN3 gene with leprosy, although a high concentration of FCN3 has been found in patients with the lepromatous form of the disease." (PMID 35622698, 2022). "We suggest that high ficolin-3 levels increase the susceptibility to leprosy playing an unfavorable role in these patients by favoring M. leprae dissemination." (PMID 28241035, 2017). "This is the first study addressing FCN3 polymorphisms and ficolin-3 levels in leprosy, indicating it as a good candidate biomarker associated with the host response against M. leprae." (PMID 28241035, 2017). "These include rs3813800 which has been associated with pulmonary infections in Chinese tuberculosis patients), rs2504778 which has been associated with hypertension, and rs28362807 which formed part of a haplotype associated with elevated Ficolin-3 levels and susceptibility to leprosy." (PMID 40340734, 2025). "A study showed that polymorphisms in the FCN3 gene cooperate to increase the concentration of ficolin-3 and may contribute to leprosy susceptibility by favoring the spread of M. leprae." (PMID 35622698, 2022). "This is the first study addressing FCN3 polymorphisms and ficolin-3 levels in leprosy." (PMID 28241035, 2017). "Previous studies have shown a contribution of genes encoding products of the lectin pathway of complement in the modulation of the susceptibility to leprosy; however, the ficolin-3/FCN3 gene impact on leprosy is currently unknown." (PMID 28241035, 2017). "We observed high concentration of ficolin-3 in leprosy patients, likely caused by polymorphisms present in intronic regions of FCN3 gene, which may contribute to leprosy susceptibility by favoring M. leprae infection." (PMID 28241035, 2017). "In this work, we investigated whether FCN3 polymorphisms and ficolin-3 serum levels play a role in the susceptibility to leprosy and observed an association between high ficolin-3 levels in serum and the disease." (PMID 28241035, 2017). "Our results lead us to suggest that polymorphisms in the FCN3 gene cooperate to increase ficolin-3 concentration and that it might contribute to leprosy susceptibility by favoring M. leprae infection." (PMID 28241035, 2017). "The present study aimed at analyzing the serum levels of mannose-binding lectin (MBL) and ficolin-3 (FCN3) in leprosy patients and their healthy family contacts in a hyperendemic region in northeastern Brazil." (PMID 35622698, 2022). "Elevated Ficolin-3 levels were also observed in ovarian tumor patients, related to shorter graft survival after kidney transplantation, in patients with Leprosy and Systemic Lupus Erythematosus, all conditions associated with inflammatory process." (PMID 30349535, 2018). "Median concentration of ficolin-3 was higher in leprosy per se (26034 ng/mL, p = 0.005) and lepromatous patients (28295 ng/mL, p = 0.016) than controls (18231 ng/mL)." (PMID 28241035, 2017). "Thus, the present study aimed to analyze the serum levels of MBL and FCN3 in leprosy patients and their healthy family contacts in a hyperendemic region in northeastern Brazil." (PMID 35622698, 2022). "We hypothesize that high ficolin-3 levels in leprosy patients probably play an unfavorable role by facilitating M. leprae dissemination." (PMID 28241035, 2017).
leprosy (continued). "In addition, high ficolin-3 levels (>33362 ng/mL) were more common in leprosy per se (34.4%) and in lepromatous patients (35.5%) than controls (19.2%; p = 0.045 and p = 0.047, respectively)." (PMID 28241035, 2017). "However, high serum concentrations of ficolin-3 were associated with the lepromatous form of the disease, which is probably caused by polymorphisms in the FCN3 gene, which may contribute to leprosy susceptibility by favoring the infection." (PMID 35622698, 2022). "There were no FCN2 or FCN3 haplotypes associated with HBV infection although we confirmed the protective association of the FCN2 promoter-exon 1 haplotype AGAAAC with leprosy per se (OR = 0.13 [95%CI=0.02–0.99], p = 0.018)." (PMID 33643280, 2020). "Higher FCN3 levels were also observed in the group of patients without leprosy reactions (37.4 μg/mL) compared to those with type 1 (33.7 μg/mL) and type 2 (36.1 μg/mL) reactions." (PMID 35622698, 2022). "However, patients with mild and transient clinical manifestations of leprosy had high FCN3 serum levels, with higher prevalence being observed in the indeterminate form, as well as an absence of physical disabilities and leprosy reactions." (PMID 35622698, 2022). "The serum values of FCN3 and MBL that were found in this study were not different between patients with leprosy and the healthy relatives, suggesting that the serum levels of these lectins did not contribute to increased susceptibility." (PMID 35622698, 2022).
Autoimmunity (6 papers, 2016 to 2024). The occurrence of an immune reaction against the organism's own cells or tissues. "Importantly, deficiency of ficolin-3 results in immunodeficiency and is associated with an higher risk (8-fold) of developing a disease and autoimmunity." (PMID 39014464, 2024). "This variant could be a risk factor for Ficolin-3 deficiency and might play a role in the observed etiology of both complete Ficolin-3 deficiency or Ficolin-3 haploinsufficiency in the response to infection and autoimmunity." (PMID 35264221, 2022). "Ficolin-3 is one of the innate immunity molecules that was thought to play a pivotal role in Streptococcus pyogenes autoimmunity and its complications; rheumatic fever (RF) and rheumatic heart disease (RHD)." (PMID 33499929, 2021). "Ficolin-3 can activate the complement system via the lectin pathway, plays roles in bacterial defenses and autoimmunity and is modulated in viral infections including HIV." (PMID 32411128, 2020). "Among these proteins, Ficolin-3 deserves special attention in the context of autoimmunity since it was initially characterized as a serum antigen target (Hakata antigen) for an autoantibody present in a Japanese patient with SLE." (PMID 27631981, 2016).
heart failure (6 papers, 2013 to 2025). Inability of the heart to pump blood at an adequate rate to meet tissue metabolic requirements. "This study provides evidence for an association of low ficolin-3 levels with advanced heart failure." (PMID 23596511, 2013). "Concordant results from two cohorts show that low levels of ficolin-3 are associated with advanced heart failure and outcome." (PMID 23596511, 2013). "First, decreased ficolin-3 levels were linked with more severe heart failure, as indicated by significant associations with high NT-proBNP levels and advanced NYHA functional class groups." (PMID 23596511, 2013). "By intersecting the findings from all three algorithms, we pinpointed four diagnostic genes for the pre-decompensation stage of heart failure: SMOC2, OGN, FCN3, and SERPINA3." (PMID 39717447, 2024). "In conclusion, biomarkers such as FCN3 and SMOC2 exhibit potential for diagnosis, emphasizing the necessity of continued investigation into their roles as diagnostic tools and therapeutic targets in heart failure management." (PMID 40297163, 2025). "However, other studies have shown that lower serum levels of FCN3 could correlate with adverse outcomes in heart failure, suggesting its potential as a prognostic marker." (PMID 40297163, 2025). "Moreover, ficolin-3 may be widely used in heart failure like NT-proBNP in the future with more and more in-depth and extensive research on ficolin-3." (PMID 34912408, 2021). "Ultimately, a total of four genes (FCN3, FREM1, MNS1, and SMOC2) exhibited significant co-expression in individuals suffering from heart failure." (PMID 40297163, 2025).